BRAF (B-Raf proto-oncogene, serine/threonine kinase)
Diseases named in the same sentence as BRAF in open-access papers (continued):
Sharing a sentence is not in itself a finding about the gene and the disease.
cancer (continued). "Although PTC is known as a BRAF associated cancer with expected active RAS/ERK pathway, search of the literature did not reveal clear pictures of activated ERK in PTC." (PMID 37114127, 2023). "Among the three RAF isoforms (ARAF, BRAF, and CRAF/Raf-1), BRAF is the most frequently mutated isoform in cancers." (PMID 37625591, 2023). "In particular, about 30% of pediatric cancers harbor BRAF/RAS mutations, while gene fusions are present in up to 60% of cases, mainly in younger patients with PTC, usually involving RET or NTRK1/3, as also ALK, BRAF and PPARG." (PMID 37046700, 2023). "Mutations in RAF or RAS are frequently identified in human cancers, and patients with these mutations are eligible for treatment with BRAF or MEK inhibitors." (PMID 37211598, 2023). "The BRAF protooncogene causes the most prevalent genomic distortion; cancers with duplication of BRAF showed increased mRNA levels of BRAF mRNA and a downstream target, CCND1, compared to tumors without duplication." (PMID 37675821, 2023). "The molecular characteristics of sporadic EOCRC differ from those of cancers in older adults, particularly regarding reduced prevalence of BRAF mutations." (PMID 39132649, 2023). "This is consistent with a growing body of evidence regarding the prognostic and predictive role of BRAF mutations across many different cancers, including malignancies of the gastrointestinal tract, lung, and skin (melanoma)." (PMID 38136294, 2023). "In particular, YAP-mediated BCL2L1 expression has been demonstrated to contribute to BRAF inhibitor resistance in different BRAF-mutated cancer cells." (PMID 37211598, 2023). "In about one-third of the patients, this was due to emerging RAS mutations and cloning of cancer cells with BRAF mutations or EGFR ectodomain mutations as an escape mechanism from EGFR inhibition." (PMID 37927605, 2023). "The high prevalence of the BRAF V600E mutation in cancers with a neuroendocrine component identifies a potential candidate population for BRAF inhibition." (PMID 37240418, 2023). "The MAPK pathway has a critical role in cancer biology, extending beyond the extensively studied BRAF mutation in melanoma." (PMID 37568654, 2023). "Frequent mutations of BRAF (most commonly the V600E mutation) substantially increase kinase activity to drive the proliferation of cancer cells." (PMID 36694209, 2023). "Mutations in the BRAF gene can cause normal cells to become cancerous, accounting for 6–8% of all human cancers." (PMID 38136350, 2023). "Genomic analyses have revealed various BRAF mutations in cancers, most of which occur in the kinase domain of the enzyme." (PMID 36856908, 2023). "Vemurafenib does not inhibit wild-type BRAF kinase and instead inhibits mutated BRAF V600E that is found in several types of cancer." (PMID 37485446, 2023). "This analysis has led to a significant shift in the treatment approach for patients with BRAF mutated cancer." (PMID 38105263, 2023). "In support of this scenario, the expression of the Tn antigen (GalNca-Ser/Thr), a precursor of Gal-GalNc, is elevated in human cancer cells with a BRAF mutation or in colon tissues from BRAFV600E−inducible mouse models." (PMID 37772997, 2023). "In 2002, BRAF mutations were found in a variety of cancers, highlighting the significance of neoplasia." (PMID 37240450, 2023). "Over 90% of activating BRAF mutations in cancer cells occur within the kinase domain at amino acid V600, most commonly resulting in V600E mutation." (PMID 37231247, 2023). "Cancers carrying BRAF mutations have increased the expression of cell cycle inhibitors, including CDKN2A, CDKN1A, and CDKN1B." (PMID 38020918, 2023). "As in adults, more aggressive cancer behavior is expected in cases harboring p.V600E or other BRAF point mutations or BRAF-like fusions (e.g., RET/PTC1, NTRK3/ETV6, ALK rearrangements), although these correlations remain unconfirmed in children." (PMID 37046700, 2023).
cancer (continued). "On the other hand, CMS1 cancers, which possessed the highest prevalence of BRAF mutations, presented a downregulated expression of claudin 4 mRNA, independently of the presence or absence of BRAF mutations (two-tailed t test p > 0.05, right)." (PMID 37998722, 2023). "By targeting the specific altered signaling pathways associated with these mutations, researchers aim to improve treatment outcomes for patients with BRAF-mutated cancers." (PMID 38021761, 2023). "The discovery of mutations in the BRAF gene in human cancer cells in 2002 laid the foundation for targeted therapy in MM." (PMID 37511202, 2023). "To date, more than 30 BRAF alterations have been associated with human cancers and are grouped according to kinase activity, which suggests mutation class also implies varying sensitivity to BRAF inhibitors." (PMID 37124503, 2023). "Dimerization of BRAF and CRAF results in increased accumulation of nuclear β-catenin in cancer-associated fibroblasts (CAFs), which further contributes to resistance against BRAF inhibitors." (PMID 38111008, 2023). "Inhibition of mutant BRAF often causes cancer cell toxicity due to the cell’s acquired dependency on mutant BRAF." (PMID 38136350, 2023). "The study assessed both the safety and efficacy of vemurafenib monotherapy in cancer patients carrying various BRAF mutations." (PMID 37111737, 2023). "These FDA-approved inhibitors do not address the clinical needs of non-BRAFV600 mutants; non-BRAFV600 mutants encompass roughly 50% of BRAF mutants in non-small cell lung cancer patients and 30% of all cancer patients contain an upstream RAS mutation." (PMID 37625591, 2023). "The role of BRAF mutations in oncogenesis and tumorigenesis has spurred the development of targeted agents, which have been successful in treating many adult cancers." (PMID 37124503, 2023). "Preclinical evidence demonstrated the potential efficacy of combining uprosertib with MEKi against a range of cancer cell lines with mutations in the BRAF or KRAS genes (NCT01935973, NCT01989598)." (PMID 37181747, 2023). "BRAF is the most frequently mutated kinase in cancer, accounting for 8% of all cancers, but attempts to target BRAF have been problematic." (PMID 37625591, 2023). "Mutations in V-RAF and its human ortholog, BRAF, were the first implicated in cancer, with hotspot mutations in V600 codons, demonstrating their oncogenic potential through the transformation of NIH3T3 cells." (PMID 37124503, 2023). "In-frame deletions comprise only 4.3% of all MAP2K1 mutations reported across all human cancers, and only 0.2% of all BRAF mutations; consequently, they remain relatively understudied." (PMID 37079639, 2023). "BRAF inhibitors target mutated BRAF, halting its aberrant function and suppressing cancer cell growth." (PMID 37764362, 2023). "Mutation of BRAF is present in 7%–10% of all human cancers, while mutated forms of ARAF and CRAF are extremely rare." (PMID 37808191, 2023). "Vemurafenib, dabrafenib, and encorafenib, first-generation RAF inhibitors, were developed and utilized as monotherapies or in conjunction with MEK inhibitors to treat cancers harboring the BRAF (V600E) mutation." (PMID 37895912, 2023). "Our work suggests HT as a protective factor against DTC risk of recurrence only in patients with BRAF-wild type carcinomas." (PMID 37190300, 2023). "Multifocality was detected in 48.2% of RET fusion-positive carcinomas, which was significantly higher than in our BRAF V600E and RAS-mutated PTCs." (PMID 37882481, 2023). "The NCCN and ATA guidelines suggest dabrafenib plus trametinib for BRAF V600 mutated carcinoma, larotrectinib or entrectinib if NTRK gene fusion is positive and pralsetinib or selpercatinib for RET-fusion positive ATC." (PMID 37076888, 2023). "BRAF (V600E) mutations were more associated with well-differentiated than poorly differentiated or moderately differentiated carcinomas (25.0% vs 3.1% vs 2.7%, P = .002)." (PMID 36862900, 2023).
cancer (continued). "It has been shown that BRAF or KRAS mutations in initiated cells co-operate with silenced TSGs by promoter hypermethylation to progress toward carcinoma formation." (PMID 37772997, 2023). "The mutation of the proto-oncogene BRAF is related with persistent activation of the MAPK/ERK pathway in cancer." (PMID 35323338, 2022). "Mutations distributed in the functional categories comprised the majority of BRAF mutations in several cancers such as THCA, SKCM, COADREAD, and LUAD." (PMID 35910024, 2022). "BRAF mutation positive cases were older age (p = 0.0198) and showed a higher frequency of poorly differentiated cancers (p < 0.0001)." (PMID 35474548, 2022). "BRAF is mutated in nearly 7% of all human cancers, and V600E point-mutation represents more than 90% of observed alterations." (PMID 36698391, 2022). "Considering that DU-4475 contains an oncogenic BRAF V600E mutation, these data suggest that DU-4475 is a mono-driver cancer cell line." (PMID 36011019, 2022). "The overall somatic mutation frequency of BRAF was 7.7% for all cancer samples (848/10,976) and 7.0% for all patients (767/10,953) across the 32 TCGA cancer types." (PMID 35910024, 2022). "The transcripts of genes related to cancer cell cytotoxicity, immune suppression, and immune cell recruitment were upregulated in the BRAF-mutated NSCLC compared to wild-type patients." (PMID 36543792, 2022). "In conjunction with their potent anti-cancer effects, cardiovascular toxicity associated with BRAF and MEK inhibition is increasingly recognized." (PMID 35492830, 2022). "The v-raf murine sarcoma viral oncogene homolog B1 (BRAF) gene containing a 15-base pair (bp) deletion at L485-P490 is the cause of several cancers." (PMID 35804932, 2022). "Our findings provide valuable insight into the clinical management and underlying pathophysiology of BRAF-driven tumors across cancers." (PMID 35565240, 2022). "They found that Dabrafenib and Trametinib induced strong apoptosis in cancer cells carrying both BRAF V600E and TERT promoter mutations but had a little proapoptotic effect in cells that only carry BRAF V600E." (PMID 35903534, 2022). "With oncogenic mutations in BRAF being associated with ∼30% of all cancers, there has been great emphasis on developing BRAF inhibitors, some of which (e.g. dabrafenib, encorafenib) are in clinical use." (PMID 35147166, 2022). "The most common single point mutation in human cancers is BRAF V600E which results in an amino acid change from valine to glutamic acid, rendering the kinase constitutively active." (PMID 36077798, 2022). "The combination of dabrafenib (a BRAF inhibitor) and trametinib (a MEK inhibitor) has shown activity in several BRAF V600E-mutated cancers." (PMID 36046845, 2022). "In this study, we used PDAC-derived BxPC-3 cells, which are one of the first identified cancer-derived cell lines, and the 15-bp deletion Mut of BRAF is shown to be a cause of carcinogenesis." (PMID 35804932, 2022). "Relying on the AACR Project GENIE dataset, the author was able to systematically investigate genetic interactions of oncogenic BRAF alleles in multiple cancer types." (PMID 36275468, 2022). "TERT promoter mutations control the apoptosis of BRAF mutant cancer cells, thereby controlling the therapeutic response to BRAF/MEK inhibitors." (PMID 35903534, 2022).
cancer (continued). "Multiple logistic regression analysis adjusted by sex and BRAF mutation showed that A variant carriers had a 3 times greater risk of early onset of cancer under the homozygote comparison model (A/A vs. T/T: OR = 3.13, 95%CI = 1.28–7.69, p = 0.034)." (PMID 35454158, 2022). "In this study, the author surveyed oncogenic BRAF mutations across cancer types using data from the AACR Project GENIE." (PMID 36275468, 2022). "BRAF is known as a common mutated kinase in various human cancer types including melanoma, colorectal cancer, thyroid cancer, non-small-cell lung cancer (NSCLC), hairy cell leukemia, and primary CNS tumors." (PMID 35158978, 2022). "As an oncogenic driver, BRAF V600 mutations account for approximately 60% of all BRAF mutations in cancer patients." (PMID 35910024, 2022). "The MAPK paradox explained that anti-BRAF agents in KRAS-mutated cancers are contraindicated because of the activation of tumorigenesis by the binding to BRAF." (PMID 36012655, 2022). "BRAF 600E mutation was identified as a common cancer-associated mutation that can be observed in many other LEATs, namely, GG, DNET, and PXA." (PMID 35372027, 2022). "Ongoing research should better define the role of new generation RAF inhibitors for patients with acquired resistance, the activity of chemo-immunotherapy or the combination of TKIs with chemotherapy or with immunotherapy in patients with BRAF-mutated cancers." (PMID 36230797, 2022). "Several studies are also investigating the activity of chemo-immunotherapy or the combination of TKIs with chemotherapy or with immunotherapy in patients with BRAF-mutated cancers." (PMID 36230797, 2022). "Other cancers with dominant BRAF mutation but at much lower mutation rate included COADREAD (10.4%), LUAD (7.2%), UCEC (4.7%), BLCA (3.2%), STAD (3.0%), LUSC (2.9%), CHOL (2.8%) and DLBC (2.1%)." (PMID 35910024, 2022). "To this end, we plotted the relative frequency of the different BRAF mutation classes for all cancer types in the project GENIE dataset." (PMID 36275468, 2022). "The cancer genome atlas (TCGA) PanCancer Atlas reported over 400 patients with cutaneous melanomas, with mutations most commonly observed in BRAF." (PMID 35326655, 2022). "Several drugs, such as vemurafenib, dabrafenib, and encorafenib, currently available to treat BRAF mutated cancer based on targeting the mutations V600E and V600K, two types of possible mutations in several cancers." (PMID 36267655, 2022). "Most bilateral cancers had bilateral BRAF V600E mutations, both in the main lesions as well as contralateral tumors, while a few harbored this mutation in the contralateral tumors only." (PMID 36230856, 2022). "Herein, inactivating mutations in RNF43 (RING-type E3 ubiquitin ligase) is an important cancer-driver mutation, not only in the familial serrated polyposis cases, but also in the sporadically occurring BRAF-mutant MSI-H CRC." (PMID 35975243, 2022). "Nevertheless, the inhibition of BRAF by small molecules in cancer patients provokes an increase of wild-type BRAF activity in healthy tissue, causing side effects and the formation of new tumors." (PMID 35408636, 2022). "In most cancers bearing BRAF mutations, patients treated with BRAF inhibitors develop disease progression within a few months from the start of treatment." (PMID 36499450, 2022). "Accumulating studies demonstrate that a BRAF inhibitor (BRAFi) can significantly improve the survival of cancer patients with BRAF mutations." (PMID 36077785, 2022). "The analyses demonstrate that the frequency of BRAF mutations greatly varies across cancer types and subtypes." (PMID 36275468, 2022). "We detected 10 cases of RAS mutation and two of BRAF K601E mutation in the present cohort, and the probability of cancer, NIFTP or WT‐UMP for RAS mutation is 80%." (PMID 35247035, 2022).
cancer (continued). "In other cancer types, BRAF signaling has been linked to TERTp mutations; therefore, a wider survey of the interaction of oncogenic alterations with TERTp mutations and telomere maintenance is warranted." (PMID 36130485, 2022). "The ROAR trial was a non-randomized, open-label, single-arm, phase 2 basket trial designed to evaluate the activity and safety of dabrafenib plus trametinib in patients with BRAF V600E-mutated rare cancers." (PMID 35955671, 2022). "BRAF mutations are known to promote cancer evasiveness and enhance oncogenic activity, providing a possible mechanism of resistance to PD‐1/PD‐L1 immunotherapy." (PMID 35044091, 2022). "The combination of BRAFi and MEKi has shown clinical activity in MM, but also in other cancers carrying BRAF mutations, such as THCA (specifically, the anaplastic subtype) and NSCLC." (PMID 35272691, 2022). "For example, being educated about BRAF mutations, how to test for them, and their impact on cancer treatment empowers patients to pressure their doctors and legislators to have access to the most appropriate therapies." (PMID 36589179, 2022). "BRAF is a serine/threonine-specific protein kinase that regulates the MAPK/ERK signaling pathway, and mutations in the BRAF gene are considered oncogenic drivers in diverse types of cancer." (PMID 36275468, 2022). "In order to assess the clinical significance of BRAF expression, we analyzed patient survival in pan-cancer and showed that increased BRAF expression was associated with poor patient overall survival (OS) in LIHC, OV, and UCEC." (PMID 35910024, 2022). "Mutations in BRAF, most frequently the valine (V) to glutamate (E) substitution at residue 600 (V600E), are identified as cancer-causing mutations in thyroid carcinoma (THCA) and skin cutaneous melanoma (SKCM)." (PMID 35910024, 2022). "Transcriptional re-activation of TBX3 is an indispensable molecular event for cancer initiation and progression, which linked BRAF/MAPK pathway activation and CXCR2 ligands-attracted MDSCs infiltration." (PMID 35332119, 2022). "Deregulation of this pathway is found in up to 30% of all human cancers and BRAF mutations can be identified in 1.5–3.5% of NSCLC patients." (PMID 36230797, 2022). "The RAS-RAF-MEK1/2-ERK1/2 (RAS/MAPK) signalling pathway is frequently dysregulated in human cancers, often by mutations in BRAF or RAS genes and therefore is an important node for development of novel oncology compounds." (PMID 35617197, 2022). "Multiple logistic regression analysis adjusted by sex and BRAF mutation showed A/A genotype carriers to have 3 times more risk of early onset of cancer (OR = 3.13, 95%CI = 1.28–7.69, p = 0.034) than T/T genotype carriers." (PMID 35454158, 2022). "First, BRAF mutation is present in cancers other than UC, such as prostatic carcinoma, which can also be detected within the urinary tract." (PMID 36072391, 2022). "BRAF mutations have been found in many cancers, hence their relevance in the field of pharmaceutical research for the purpose of developing new targeted drugs." (PMID 36077798, 2022). "BRAF mutation in position V600E, which carried about 80% of alteration and V600 K about 10–20%, were responsible for development of cancer in young people, mainly the tumors appear in the parts of body that were not commonly exposed to sunlight." (PMID 36267655, 2022). "Because of the large number of samples in the AACR Project GENIE dataset, the author was also able to systematically assess mutational co-occurrence of BRAF mutations with mutations in other genes in multiple cancer types." (PMID 36275468, 2022). "GLANT6 mRNA expression showed no strong correlation with other GALNTs or mucins but was significantly higher in KRAS mutated or BRAF wild-type early-stage cancers." (PMID 35692787, 2022). "KRAS, NRAS and BRAF mutations were frequently identified in high cancer cell fractions and considered driver mutations in MM." (PMID 35158933, 2022).